SNORD42B (small nucleolar RNA, C/D box 42B)
Synonyms: U42B; RNU42B
Gene: Small nucleolar RNA gene on chromosome 17 (28,720,550 to 28,720,616, forward strand). Ensembl gene ENSG00000238423.
Gene Ontology:
Biological process: RNA processing
Cellular component: nucleolus
Homologues: Orthologues: chimpanzee SNORD42 (100% identical), macaque SNORD42 (97% identical), dog SNORD42 (96% identical), rat Snord42b (94% identical), mouse Snord42b (93% identical), rabbit SNORD42 (93% identical), guinea pig SNORD42B (91% identical), pig SNORD42 (90% identical), rabbit SNORD42 (87% identical), zebrafish SNORD42 (73% identical). Paralogues in human: SNORD42 (88% identical), SNORD42 (69% identical), SNORD42A (61% identical).